MMP8 (matrix metallopeptidase 8)
Diseases named in the same sentence as MMP8 in open-access papers (continued):
Sharing a sentence is not in itself a finding about the gene and the disease.
cancer (continued). "In breast, skin and oral tongue cancer, substantial evidence reveals that MMP8 inhibits invasion and proliferation of cancer cells and reduces the probability of metastasis by eliminating non-structural substrates." (PMID 35884594, 2022). "Most studies correlate MMP8 to cancer advancement by determining the mRNA expression in tissue samples, as well as protein analysis in either tissue or blood samples." (PMID 34356991, 2021). "When we looked at extracellular proteases, matrix metallo-proteases in particular, we observed that Mmp-14, Mmp-19 and Mmp-8 were also up-regulated in SSMs in cancer." (PMID 34168645, 2021). "The secretion of ECM-remodeling enzymes, such as MMP9 (gelatinase B or type IV collagenase), MMP8 (Neutrophil collagenase or Collagenase 2), CathG and NE, paves the way for cancer cell migration and angiogenesis." (PMID 34572138, 2021). "To date, the function of MMP8 in cancer progression has been confusing as various types of cancers demonstrated different prognosis outcome, despite presenting a similarly high level of MMP8 expression." (PMID 34356991, 2021). "It has been reported that MMP8 behaved differently in cancers depending on their tissue of origin and was a potential prognostic factor." (PMID 33816503, 2021). "For example, in the skin, breast and oral tongue cancers, the presence of MMP8 seems to confer protective anti-tumoral activities to patients by limiting cancer cell growth, invasion and spread." (PMID 34356991, 2021). "MMP8 also inactivates integrin beta-1 resulting in reduced invasiveness in multiple cancer cell lines, with the most prominent effect seen in prostate cancer." (PMID 34059618, 2021). "On the other hand, MMP-8 was shown to exert anti-proliferative and inhibitory activities on the spread of cancer cells to tissues, with a net inhibitory effect on metastasis." (PMID 33042020, 2020). "The use of MMP8 as an adjuvant in cancer drug treatment poses unappreciated potential and should be further studied." (PMID 31514474, 2019). "The collective evidence reveals that in breast, skin and oral tongue cancer, MMP8 inhibits cancer cell invasion and proliferation, and protects patients from metastasis via cleavage of non-structural substrates." (PMID 31514474, 2019). "In vitro and in vivo (murine) studies are reviewed to emphasize the molecular mechanisms of MMP8 and finally, the use of MMP8 in all levels of cancer therapy is discussed." (PMID 31514474, 2019). "In these cancers, MMP8 slows the metastatic process both in vivo and in vitro, which explains why patients benefit from MMP8." (PMID 31514474, 2019). "SNPs, which modulate MMP8 transcription and activity, seem to play the strongest role in cancer prognosis and are beneficial for breast, bladder and gastric cancer patients but detrimental in ovarian cancer patients." (PMID 31514474, 2019). "By applying systematic review guidelines and methods, we gathered the original research articles published on MMP8 related to cancer and provide a comprehensive compilation of the current knowledge on the subject." (PMID 31514474, 2019). "The molecular mechanisms of MMP8 in cancer further emphasize its role as an important regulator of bioactive molecules." (PMID 31514474, 2019). "The studies on MMP8 in the circulation of cancer patients have predominantly investigated MMP8 in blood, specifically in plasma and serum." (PMID 31514474, 2019). "High serum MMP8 levels seem to hinder the survival of patients with various cancers of the digestive and urinary systems." (PMID 31514474, 2019). "Angiogenesis is a major target in cancer treatment and MMPIs have been developed against proangiogenic MMPs such as MMP8 and MMP9." (PMID 31514474, 2019). "Some MMPs had very high numbers of transcripts present (gene cluster A), while six MMPs in gene cluster C (MMP27, MMP21, MMP20, MMP26, MMP23A, and MMP8) featured scant numbers of transcript copies across any cancer tissue." (PMID 31200666, 2019).
cancer (continued). "The MMP8 is not only produced by neutrophils but also synthesized by a series of malignant tumor cells." (PMID 31638929, 2019). "We applied systematic review guidelines to study MMP8 in cancer including the use of MMP8 as a prognostic factor or as a target/anti-target in cancer treatment, and its molecular mechanisms." (PMID 31514474, 2019). "The MMP-8 serves as one of the most efficient collagenases and plays an essential role in carcinoma invasion and metastasis." (PMID 31638929, 2019). "The enzyme activities of MMP2 and 3 in GA cancer tissues were higher than those in normal tissues, and MMP8 enzyme activity was lower than those in normal tissues (MMP2, p=0.028; MMP3, p=0.012; MMP8, p=0.0029." (PMID 29285307, 2017). "This work represents the first study exploring the role of MMP-8 in a spontaneous cancer mouse model." (PMID 25848906, 2015). "MMP-8 plays an important role in progression and regulation of a variety of diseases, inflammatory response, blood pressure and cancer progression." (PMID 25432491, 2014). "The majority of MMPs are pro-tumorigenic in cancer, although certain individual MMPs, such as MMP-8, can assume an opposite protective role." (PMID 23516511, 2013). "This selectivity is important since, in contrast to MT1-MMP, MMP-8 displayed an anti-tumorigenic property for certain cancer types." (PMID 23516511, 2013). "The anti-tumorigenic and anti-metastatic role emphasizes the notion that the role of MMP8 in cancer is far more puzzling than originally thought." (PMID 18366705, 2008). "This was the first report of a MMP having a protective role in tumorigenesis, so validating MMP-8 as an anti-target in cancer therapy." (PMID 17375198, 2007). "It is concluded that the assay for MMP-8 and -9 described here will permit the evaluation of these proteases as prognostic markers in cancer." (PMID 7734294, 1995). "Accordingly, the MMP-8/TIMP-1 ratio was reduced in individuals with incident cancer." (PMID 42162053, 2026). "MMP8 plays a pivotal role in both normal physiological processes and pathological conditions, including cardiovascular, musculoskeletal, renal, digestive, and respiratory disorders, as well as cancer." (PMID 40136514, 2025). "Downregulation of MMP8 expression (−4.0), as seen in our study, may contribute to the disruption of intercellular adhesion, facilitating the migration of cancer cells and promoting metastatic spread." (PMID 39858031, 2025). "MMP-8 is a multifaceted protease with both cancer-promoting and protective facilities, and it may have different roles depending on the type of cancer." (PMID 39917664, 2024). "MMP-8, the neutrophil collagenase, is an important regulator of innate immunity that has onco-suppressive functions in cancers, and inhibition of MMP-8 might exert complicated effects on innate immunity." (PMID 37766868, 2023). "MMP-8 plays a varied prognostic role in cancers of the gastrointestinal tract." (PMID 35328734, 2022). "Staining in the cancer cells was clearly distinguishable, and MMP-8 expression was strong in PMNs." (PMID 35328734, 2022). "In addition, the intracellular C-terminus of ephrin-B1, which was necessary to cancer invasion, was reported to manage the MMP8 liberation from cells through activating the cell trafficking regulator Arf1." (PMID 35884594, 2022). "Moreover, MMP-8 expression in cancer cells served as an independent positive prognostic factor in PDAC." (PMID 35328734, 2022). "However, previously reported substrate cleavage by MMP8 leads to various effects depending on the cancer type and it is possible that the mechanisms are disease specific." (PMID 34059618, 2021). "In addition to regulating apoptosis and immune response, MMP8 also plays a protective role in lung inflammation, cancer progression, and wound healing." (PMID 34803684, 2021). "Overall analysis indicated that the relationship between the three MMP-8 variants and cancer susceptibility was not significant." (PMID 31638929, 2019).
cancer (continued). "In conclusion, these findings suggested that the MMP-8 rs11225395 polymorphism is associated with elevated susceptibility to cancer in non-Asian populations." (PMID 31590330, 2019). "Systemic changes in MMP8 levels after cancer treatment might be explained by the changes in systemic inflammation." (PMID 31514474, 2019). "MMP-8 C-799 T, Lys460Thr, and Lys87Glu variants are not participant with the susceptibility of cancer." (PMID 31638929, 2019). "For the following cancers, only single studies on the role of MMP8 exist." (PMID 31514474, 2019). "MMP8 is nowadays considered an anti-target in cancer drug development." (PMID 31514474, 2019). "Taken together, based on the currently published data, our study showed evidence that MMP-8 C-799 T, Lys460Thr, and Lys87Glu variants are not participant with the susceptibility of cancer." (PMID 31638929, 2019). "We conclude, that MMP8 has differing effects on cancers depending on their tissue of origin." (PMID 31514474, 2019). "MMP-8, also known as collagenase-2 or neutrophil collagenase, is a protease that is mainly produced by neutrophils, but is also involved in several pathologies, including cancer." (PMID 24788523, 2014). "More importantly, the AHLR biosensor cannot be cleaved by the anti-cancer MMP-8 in vitro." (PMID 23516511, 2013). "Secondly, in clonal cell lines derived from MDA-MB-435 cancer cells that display high (M-4A4) or low (NM-2C5) metastatic ability, overexpression of MMP-8 reduced the metastatic ability of M-4A4 cells, whereas ribozyme-mediated gene knockdown of MMP-8 enhanced metastasis of the NM-2C5 line." (PMID 23632023, 2013). "MMP-8 is expressed in many cancer types and may protect against cancer spread by regulating tumour metastasis." (PMID 23216739, 2012). "In this case, the association of this cluster of genes with LPHN2 has suggested that LPHN2 may be a regulatory point for the modulation of genes with important roles in cancer, including MMP8 and SOX11." (PMID 21226949, 2011). "In addition, a completely protective role in cancer has been reported in MMP-8 KO mice, which exhibited enhanced carcinogenesis induced by chemical carcinogens." (PMID 22015555, 2011). "Nevertheless, it seems unlikely that changes in MMP8 expression alone could affect the metastatic behaviour of cancer cells so dramatically." (PMID 18366705, 2008). "Therefore, further investigation with larger patient cohorts is clearly needed to better understand the paradoxical role of MMP8 in cancer metastasis." (PMID 18366705, 2008). "Furthermore, other proteases may work together with MMP8 to facilitate its effects in various cancers as demonstrated in the protease web generated by PathFINDer." (PMID 34059618, 2021). "The studies published to date, suggest that high MMP8 protein levels might predict better survival for tongue and some breast cancer patients, but they provide a worse prognosis in hepatocellular and ovarian cancers." (PMID 31514474, 2019). "However, many cancer therapies modulate MMP8 levels—this might present changes in systemic inflammation." (PMID 31514474, 2019). "Furthermore, neutrophils also release MMP-8 (Collagenase-2) in cancer cases." (PMID 31010242, 2019). "MMP family members, such as MMP2, MMP8, and MMP9, have important roles in degrading the extracellular matrix (ECM), contributing to migration and metastasis formation in various cancers." (PMID 40566630, 2025). "Furthermore, SFV infection of cancer cells downregulated several migration- and invasion-associated genes in macrophages (e.g., Mmp8, Mmp10 and Mmp12), particularly in the SFV/IFNγ group, suggesting that this approach may inhibit cancer cell dissemination and metastasis." (PMID 40547518, 2025). "STAT5A signaling, CSPG4, MMP-1, MMP-3, MMP-8, MMP-9, and LUM are all involved in cancer cell migration, invasion, and metastasis, while PKM supports the growth and survival of cancer cells by favoring aerobic glycolysis." (PMID 39201614, 2024).
cancer (continued). "Normal lung cells express relatively lower levels of matrix metalloproteinase 8 (MMP8), and probably increase its secretion when cells are exposed to a pro-MMP activator during the transformation into carcinoma cells." (PMID 34356991, 2021). "Despite the general notion that collagenases (MMP1, MMP8 and MMP13) are key players in cancer biology, relatively little is known about collagenases in PDAC." (PMID 32325664, 2020). "Other than NE and CG, neutrophil released matrix metalloproteases (MMP) such as MMP-8 and MMP-9 are also found to be involved in ECM remodeling to facilitate cancer progression." (PMID 31010242, 2019). "With MMP-8 being the first MMP reported to have a protective role in tumorigenesis, the recognition of further MMP anti-targets in cancer continues." (PMID 17375198, 2007). "Macrophages promote cancer invasion by secreting MMPs (MMP12, MMP8 and MMP14)." (PMID 37324952, 2023). "Due to the critical role of MMP8 and MAPK3 in cancer development and metastasis, kaempferol and its glycosylated forms could be considered drug candidates for cancer therapy." (PMID 37090055, 2023). "After CRISPR/Cas9-mediated disruption of IE8, cancer cells showed a switch in the MMP expression signature, specifically downregulating the pro-invasive MMP1 gene and upregulating the antitumorigenic MMP8 gene, resulting in reduced invasive ability and collagen degradation." (PMID 38017545, 2023). "Cancer can produce a wide spectrum of proteases, including MMP-1, MMP-3, MMP-7, MMP-8, and MMP-14." (PMID 34769032, 2021). "The previous review articles on the role of MMP8 in cancer are outdated, do not focus solely on MMP8 and are not systematic reviews on the subject." (PMID 31514474, 2019). "Because some MMPs, such MMP-8 and MMP-12, can be beneficial as antitumor targets, a broad MMP targeting is not recommended, as already demonstrated by the unsuccessful use of broad MMP inhibitors in experimental cancer assays." (PMID 24578639, 2014). "Another interesting pathways activated in both cancer cell lines is the extracellular matrix organization which involves up-regulation of different collagen genes like (COL1A1, COL1A2, COL3A1), and matrix metallopeptidase like (MMP8, MMP14)." (PMID 25077705, 2014). "Nothing has been published thus far about SNPs for MMP-8 and cancer, but three MMP-8 promoter haplotypes (MMP-8–799C>T, MMP-8+17C>G and MMP-8−381A>G) have been found to be associated with preterm rupture of membranes in delivery, indicating a functional role on MMP-8 expression." (PMID 16940985, 2006). "In contrast, Mmp8 and Mmp12 have been ascribed a protective role in cancer, although this may be independent of their ability to shape the ECM." (PMID 31505876, 2019). "However, the functions of MMP8 seem to be highly diverse, and thus, no clear consensus for its role in cancer has been reached." (PMID 31514474, 2019). "The use of MMP8 in treatment selection and for the evaluation of harmful post-operative reactions has not been fully examined in various cancers but it might be useful in those cancers where MMP8 has been shown to play a role." (PMID 31514474, 2019). "Therefore, the AHLR biosensor reports the pro-invasive activity of MT1-MMP but not the protective activity of MMP-8 and, thus, can be applied to profile the invasiveness of cancer cells." (PMID 23516511, 2013). "Therefore, the expected correlation in presence of MMP-8 and MMP-9 was confirmed by the high correlation between both antigen levels (ρ 0.810, P⩽0.001, n=158), and the similar distribution according to the different cancer subgroups." (PMID 16538217, 2006). "Genes upregulated by >1.5‐fold in cancer tissues rather than in normal intestinal mucosae include Wnt signaling‐related genes such as Fzd1 (fold change [FC], 5.6), Myc (FC, 2.6), Ccnd1 (FC, 1.6), Mmp2 (FC, 10.4), Mmp7 (FC, 16.0), Mmp8 (FC, 12.9), Mmp12 (FC, 52.2), and Spp1 (FC, 149.3)." (PMID 35274815, 2022).
cancer (continued). "However, none of these studies examined how changes in the level of MMP8 affected the cancer cells." (PMID 31514474, 2019). "We found that MMP-8 immunoexpression in cancer cells combined with a low plasma CRP level (<10 mg/L) is a strong predictor of a favourable outcome in PDAC, whereas no MMP-8 expression and an elevated CRP level (≥10 mg/L) predicts a poor prognosis." (PMID 35328734, 2022). "Moreover, these agents did not interfere with MMP-8, the protective MMP enzyme in cancer." (PMID 28677624, 2017).